TYROBP (transmembrane immune signaling adaptor TYROBP)
Diseases named in the same sentence as TYROBP in open-access papers (continued):
Sharing a sentence is not in itself a finding about the gene and the disease.
tauopathy (9 papers, 2019 to 2025). Neurodegenerative disorders involving deposition of abnormal tau protein isoforms (tau proteins) in neurons and glial cells in the brain. "Our lab characterized the in vivo consequences of TYROBP deficiency in standard AD-related mouse models of cerebral amyloidosis or tauopathy." (PMID 36002854, 2022). "C1q is upregulated in amyloidosis and tauopathy mouse models and our team observed that a deficiency of TYROBP induces a dramatic reduction of C1q in both APP/PSEN1 and MAPTP301S mice." (PMID 36002854, 2022). "Using transgenic or viral approaches, we characterized in mice the effects of TYROBP deficiency on the phenotypic and pathological evolution of tauopathy." (PMID 30283031, 2019). "Further investigations of clinico-molecular and clinico-pathological correlations will be required in order to determine what underlies the “improved function yet worsening biomarkers” situation that occurs in TYROBP-deficient MAPTP301S tauopathy mice." (PMID 30283031, 2019). "In addition to reviewing the structure and localization of TYROBP, we discuss our recent progress using mouse models of either cerebral amyloidosis or tauopathy that were engineered to be TYROBP-deficient or TYROBP-overexpressing." (PMID 36002854, 2022). "For example, tyrosine motif binding protein (TYROBP) knockout resulted in reduced C1q, improved synaptic function and learning and memory outcomes, despite worsening of tauopathy." (PMID 33740987, 2021). "It is also logical to compare the effects of TYROBP or TREM2 deficiency on tauopathy, although this is somewhat difficult due to discrepant findings reported to date from Trem2 KOs crossed with mouse models of tauopathy." (PMID 30283031, 2019). "This network contains the AD hub-gene TYROBP and it is highly enriched for the complement cascade and genes differentially expressed in microglia from AD patients or mouse models of AD (FXFAD model;) or tauopathies (hMAPT -P301S model;)." (PMID 32166339, 2020).
gastric cancer (7 papers, 2020 to 2022). A primary or metastatic malignant neoplasm involving the stomach. "have reported that TYROBP is negatively correlated with the prognosis of gastric cancer and positively associated with the predictive biomarkers of gastric cancer immunotherapy." (PMID 35185791, 2022). "Based on these results, we further identified TYROBP and C1QB as the two key genes with prognostic value in gastric cancer." (PMID 33014868, 2020).
Sepsis (7 papers, 2011 to 2025). Sepsis is defined as life-threatening organ dysfunction caused by a dysregulated host response to infection. "Bioinformatics analysis underscored the pivotal role of activated hemocytes in diagnosing pediatric sepsis, with SPI1, TYROBP, and FCER1G co‐expression influencing the disease's pathophysiology by modulating neutrophil and platelet activity." (PMID 40626122, 2024). "Notably, elevated expression levels of SPI1, TYROBP, and FCER1G were observed in pediatric sepsis or septic shock, with positive correlations between SPI1, FCER1G, and TYROBP." (PMID 40626122, 2024).
amyloid (6 papers, 2018 to 2025). "The ability of TransComp-R to identify well-known hub genes, such as TREM2 and TYROBP, identified through other computational methods provided a positive confirmation of our modeling methodology, especially given analysis using a traditional amyloid mouse model dataset." (PMID 34658769, 2021).
cognitive deficits (6 papers, 2008 to 2025). "A previous study among 3,220 older Finns did not detect any association between monoallelic TYROBP deletion and cognitive impairment." (PMID 40301889, 2025).
diabetes (6 papers, 2020 to 2025). "First, we selected the central core sites in the PPI network of AS, DN, DR and found six characteristic genes of diabetes (TYROBP, LCP2, CCL2, CD44, RPL3, CDK4)." (PMID 36755923, 2023). "Drugs closely related to diabetes, such as Fenretinide, Dimethylamine parthenolide, Chelerythrine, etc., have obvious positive correlation with LCP2, TYROBP, RPL3, CDK4, and CD44." (PMID 36755923, 2023).
Parkinson disease (6 papers, 2013 to 2024). A progressive degenerative disorder of the central nervous system characterized by loss of dopamine producing neurons in the substantia nigra and the presence of Lewy bodies in the substantia nigra and locus coeruleus. "In addition to AD, TYROBP was identified as a hub gene in a microglial module conserved between human aging and neurodegenerative diseases, including Parkinson's disease (PD) and HD." (PMID 38459557, 2024).
schizophrenia (6 papers, 2012 to 2021). A major psychotic disorder characterized by abnormalities in the perception or expression of reality. "The gene encoding zinc finger binding protein ZNF804A is a well-recognized schizophrenia risk gene knockdown of which has been shown to decrease TYROBP protein expression in a variant CNS catecholaminergic cell line." (PMID 34321086, 2021). "This is of further interest as TYROBP has also been linked to schizophrenia." (PMID 31920576, 2019). "In the present study, we report gene expression and association analyses of both TYROBP and TREM2 in patients with AD and schizophrenia." (PMID 26332043, 2015). "TYROBP expression in patients with AD and schizophrenia was similar to that in their respective control groups (P = 0.44 and P = 0.13, respectively)." (PMID 26332043, 2015). "TYROBP knockout mouse studies reveal deficits in cognitive functions and prepulse inhibition, symptoms that have been manifested in many schizophrenia patients." (PMID 23282246, 2012). "The objective of this study was to reveal the involvement of TYROBP and TREM2 in the pathophysiology of AD and schizophrenia." (PMID 26332043, 2015). "We performed genotyping of 3 tag SNPs (rs8113524 and rs3817624 in TYROBP and rs2234256 in TREM2) in 796 patients with schizophrenia and 510 controls (unrelated Japanese participants)." (PMID 26332043, 2015). "In the present study, we found that TREM2 was more highly expressed in leukocytes of patients with AD and schizophrenia, which were of different disease and age groups, whereas TYROBP expression was not altered in these groups." (PMID 26332043, 2015). "TYROBP expression was not changed in either AD or schizophrenia." (PMID 26332043, 2015). "We could not find significant association between TYROBP and TREM2 gene polymorphisms and schizophrenia." (PMID 26332043, 2015).
demyelinating disease (5 papers, 2013 to 2025). A broad group of disorders that affect the myelin sheaths that cover the neurons. "These animal models may suggest a beneficial role of TREM2 in demyelinating diseases, and considering our data indicating TREM2/TYROBP as an orthologue CPZ/MS pathway, upregulation of TREM2/TYROBP may be also beneficial in MS." (PMID 30114292, 2018). "ALS-increased DEGs were also enriched for genes related to phagosome, vesicle, plasma membrane, TYROBP microglia network, CD3/TCR zeta chain phosphorylation, demyelinating disease, macrophage activation and the nonsteroidal anti-inflammatory drug lumiracoxib (p < 0.05)." (PMID 40700130, 2025).
Leukoencephalopathy (5 papers, 2009 to 2024). This term describes abnormality of the white matter of the cerebrum resulting from damage to the myelin sheaths of nerve cells. "In our analyses, TREM2, TYROBP, and GRN associated with leukoencephalopathy and FTD, show correlated gene expression, however, SMCR8 and WDR41, known to form a complex with C9orf72, did not." (PMID 38469573, 2024).
renal cell carcinoma (5 papers, 2019 to 2023). "In addition, the high expression of TYROBP in patients with renal cell carcinoma is associated with poor prognosis, suggesting that TYROBP may be involved in the occurrence and development of renal cell carcinoma and can be used as a target for diagnosis and treatment." (PMID 36595751, 2022).
leukemia (4 papers, 2014 to 2021). A malignant (clonal) hematologic disorder, involving hematopoietic stem cells and characterized by the presence of primitive or atypical myeloid or lymphoid cells in the bone marrow and the blood. "Herein we show that in leukemia cells ERG overexpression promotes a mesenchymal-like gene expression signature that includes: CD24, CD44, ITGA10, ITGB5, ITGB3, ITGA2B and the morphogenic-associated genes, such as SHANK3, TYROBP." (PMID 24504051, 2014).
diabetic nephropathy (3 papers, 2023 to 2025). "TYROBP was identified by bioinformatics analysis as a potential candidate gene for lupus nephritis and a candidate gene for tubulointerstitial fibrosis in diabetic nephropathy, possibly associated with the epithelial-mesenchymal transition of the renal tubular epithelium." (PMID 37113991, 2023). "Numerous studies have identified TYROBP as a biomarker for diabetic nephropathy and retinopathy." (PMID 40284755, 2025). "Our study explored the same platform GEO dataset for diabetic nephropathy bioinformatics analysis and identified eight potential key genes (TYROBP, ITGB2, CD53, IL10RA, LAPTM5, CD48, C1QA, and IRF8), screened eight transcription factors, and identified 93 miRNA nodes." (PMID 37113991, 2023). "However, TYROBP was expressed at low abundance in other types of kidney disease including minimal change disease (MCD), diabetic nephropathy (DN), focal segmental glomerular sclerosis (FSGS) and membranous nephropathy (MN)." (PMID 36978098, 2023).
Insulin resistance (3 papers, 2021). Increased resistance towards insulin, that is, diminished effectiveness of insulin in reducing blood glucose levels. "TYROBP is strongly related to insulin resistance and is mainly involved in the regulation of immune responses and integrin-mediated signaling." (PMID 34093637, 2021).
leukodystrophies (3 papers, 2021 to 2024). "Leukodystrophies related to bi-allelic loss-of-function mutations in CSF1R, TREM2, TYROBP, LRRC33/NRROS or USP18 can be categorized as primary microgliopathies." (PMID 34282843, 2021).
melanoma (3 papers, 2021 to 2022). A malignant, usually aggressive tumor composed of atypical, neoplastic melanocytes. "Although there was no direct evidence for the association between TYROBP and melanoma, given the important association between these hub genes and immune infiltration, we regard them as potential therapeutic targets for patients with BRAF mutations." (PMID 36531226, 2022).
multiple sclerosis (3 papers, 2019 to 2020). A progressive autoimmune disorder affecting the central nervous system resulting in demyelination. "The expression levels of TPGRL1 and TYROBP and IL-8 and TNF-α increased for diabetic patients, whereas TYROBP and USP16 and IL-6, IL-8, CSF2, and TNF-α increased for multiple sclerosis patients." (PMID 32517215, 2020). "In vivo, expression levels of TERC and TERC target genes (TYROBP, TPRG1L and USP16) are upregulated in patients with inflammation-related diseases such as type II diabetes and multiple sclerosis." (PMID 31294790, 2019). "For diabetic patients, TPRG1L and TYROBP were upregulated, whereas TYROBP and USP16 were upregulated in multiple sclerosis patients." (PMID 31294790, 2019).
Onset (3 papers, 2023 to 2025). The age group in which disease manifestations appear. "Furthermore, microglial TYROBP, a network hub and driver of sporadic late-onset AD, was highly expressed in TS Micro." (PMID 40036868, 2025).
ovarian carcinoma (3 papers, 2021 to 2025). A malignant neoplasm originating from the surface ovarian epithelium. "By PPI network and MCODE module, TYROBP, ITGB2, C1QB, C1QA, CD53 and CD163 have top connectivity among all DEGs and are considered to have important relationship to immune response in ovarian cancer." (PMID 33987033, 2021). "TYROBP, ITGB2, C1QB, C1QA and CD53 in module B have the top connectivity among all DEGs and are considered to have important relationship to immune response in ovarian cancer." (PMID 33987033, 2021).
systemic lupus erythematosus (3 papers, 2009 to 2025). An autoimmune multi-organ disease typically associated with vasculopathy and autoantibody production. "The most enriched pathways in the GSE109857 dataset were the cell cycle checkpoints, PLK1 pathway, systemic lupus erythematosus, and TYROBP causal network in microglia." (PMID 41438761, 2025).
atrial fibrillation (2 papers, 2022 to 2024). A disorder characterized by an electrocardiographic finding of a supraventricular arrhythmia characterized by the replacement of consistent P waves by rapid oscillations or fibrillatory waves that vary in size, shape and timing and are accompanied by an irregular ventricular response. "TYROBP promotes the development of inflammation-mediated atrial fibrillation through PI3K-AKT pathway." (PMID 38549127, 2024). "CXCR4 and TYROBP might be involved in the development of atrial fibrillation by affecting inflammation‐related signalling pathways and may serve as targets for early diagnosis and preventive treatment." (PMID 35607269, 2022). "CXCR4 and TYROBP may activate the PI3K/AKT pathway by promoting the expression of inflammatory indicators, further leading to the development of atrial fibrillation." (PMID 35607269, 2022).
autoimmune disease (2 papers, 2022 to 2025). A disorder resulting from loss of function or tissue destruction of an organ or multiple organs, arising from humoral or cellular immune responses of the individual to their own tissue constituents. "Genetic research also reveals that genetic variations associated with TYROBP may increase susceptibility to autoimmune diseases." (PMID 39805933, 2025). "Furthermore, TYROBP is crucial in autoimmune diseases like HT, influencing immune responses involving macrophages and NK cells." (PMID 39805933, 2025).
Autoimmunity (2 papers, 2025). The occurrence of an immune reaction against the organism's own cells or tissues. "Specific genetic markers identified in genome-wide association studies (GWAS) related to autoimmunity may enhance disease risk by influencing molecules in immune regulation pathways, such as TYROBP." (PMID 39805933, 2025).
COVID-19 (2 papers, 2021 to 2024). A disease caused by infection with severe acute respiratory syndrome coronavirus 2. "Seven common key genes were found in these four hub gene sets, including FCER1G, ITGAM, LCP2, LILRB2, MNDA, SPI1, and TYROBP, which were considered core targets of IC and COVID-19." (PMID 38267482, 2024).
glaucoma (2 papers, 2020 to 2023). Increased pressure in the eyeball due to obstruction of the outflow of aqueous humor. "Manipulating TYROBP and TREM2 is a promising strategy to define functions of microglia in glaucoma and a possible avenue for treatment." (PMID 32450896, 2020).
Granuloma (2 papers, 2015 to 2023). A compact, organized collection of mature mononuclear phagocytes, which may be but is not necessarily accompanied by accessory features such as necrosis. "Their data revealed that the M2 polarization of CCL18-positive macrophages with TYROBP and TGF-β expression was crucial for granuloma formation." (PMID 38067175, 2023).
proteinopathies (2 papers, 2019 to 2022). "Remarkably, constitutively TYROBP-deficient mice provided a model of genetic resilience to either of the defining proteinopathies of AD." (PMID 36002854, 2022). "However, TYROBP deficiency also demonstrated a beneficiary role on other related proteinopathies of AD, like tau, synaptic integrity, and the lysosomal processes." (PMID 30743990, 2019).
staphylococcus aureus infection (2 papers, 2021 to 2022). An infectious process in which the bacteria Staphylococcus aureus is present. "In the aspect of KEGG, the genes related to TYROBP and SOX6 are mainly enriched in the staphylococcus aureus infection, phagosome, and cell adhesion molecules." (PMID 36595751, 2022).
Adult onset (1 paper, 2022). Onset of disease manifestations in adulthood, defined here as at the age of 16 years or later. "There are obvious parallels with another adult-onset microgliopathy, Nasu–Hakola disease, which is associated with mutations in TREM2 or the adaptor, TYROBP, which lie downstream of CSF1R in regulation of microglial survival." (PMID 35333324, 2022).
Cirrhosis (1 paper, 2022). A chronic disorder of the liver in which liver tissue becomes scarred and is partially replaced by regenerative nodules and fibrotic tissue resulting in loss of liver function. "Seven DEGs (TYMP, TYROBP, CD14, TGFBI, LILRA2, GNLY, and GZMB) were common to HCC, cirrhosis, and CHB when compared to healthy controls." (PMID 35265561, 2022).
corticobasal syndrome (1 paper, 2013). Corticobasal syndrome (CBS) is a rare neurodegenerative disease characterized by multifaceted motor system dysfunctions and cognitive defects such as asymmetric rigidity, bradykinesia, limb apraxia, and visuospatial dysfunction. "The CSF1R (a microglial receptor) where malfunctioning is associated with a corticobasal syndrome called hereditary diffuse leukoencephalopathy with spheroids was reported to be cosignaling with TYROBP." (PMID 23662159, 2013).
Encephalopathy (1 paper, 2017). Encephalopathy is a term that means brain disease, damage, or malfunction. "Evidence associating TYROBP to LOAD notwithstanding, it is important to recognize that most TYROBP mutations (as well as TREM2 mutations) represent loss-of-function mutations that result not in AD but in an osteopathy/encephalopathy known as Nasu–Hakola disease (NHD)." (PMID 28612290, 2017).
epilepsy (1 paper, 2020). A brain disorder characterized by episodes of abnormally increased neuronal discharge resulting in transient episodes of sensory or motor neurological dysfunction, or psychic dysfunction. "The role of TYROBP in epilepsy is still unknown and deserves further exploration." (PMID 33225612, 2020).
flu (1 paper, 2021). "We noted increased expression of genes related to cytotoxicity, activation and inflammation—such as GZMB, GNLY, TYROBP, HOPX, and CCL5—in the CD8 EMRA-like two cluster that was expanded in CAP-flu." (PMID 34424199, 2021).
head and neck squamous cell carcinoma (1 paper, 2019). A squamous cell carcinoma that arises from any of the following anatomic sites: lip and oral cavity, nasal cavity, paranasal sinuses, pharynx, larynx, and salivary glands. "Interestingly, all five of these genes, CD74, C1QB, FCER1G, TYROBP, and C1QA are part of a protein-protein interaction network comprised of 20 proteins in total that are found only in head and neck squamous cell carcinomas but not in normal head and neck specimens." (PMID 31139325, 2019).
hypertrophic cardiomyopathy (1 paper, 2021). A condition in which the myocardium is hypertrophied without an obvious cause. "TYROBP (TYRO protein tyrosine kinase-binding protein) shows significant increasing expression levels in model HCM (Hypertrophic cardiomyopathy) rats and affected the immune system significantly." (PMID 34844599, 2021).
Immunodeficiency (1 paper, 2023). Failure of the immune system to protect the body adequately from infection, due to the absence or insufficiency of some component process or substance. "Despite NSG mouse immunodeficiency, four of the PDX models partially reconstructed the vascular and immune-microenvironment observed in patients, among which the macrophagic TREM2/TYROBP axis expression, recently linked to immunosuppression." (PMID 37377921, 2023). "Strikingly, the best contributor genes to MPC2 involved TREM2/TYROBP, an axis associated with immunosuppression, suggesting that MPC2 might correspond to tumor associated macrophage (TAM) infiltrates despite the immunodeficiency of NSG mice." (PMID 37377921, 2023).
keloid (1 paper, 2022). An irregularly shaped, elevated mark on the skin caused by deposits of excessive amounts of collagen during wound healing. "Furthermore, two modules of macrophages (Module2: highly expresses RNASE1, C1QA, CD163, CD14, C1QC, FCGRT, and MS4A7; Module10: highly expresses APOC1, CTSB, CTSL, and TYROBP), which exhibited the characteristics of TAMs, increased significantly in keloid." (PMID 35990663, 2022).